UMOD (uromodulin)
Diseases named in the same sentence as UMOD in open-access papers (continued):
Sharing a sentence is not in itself a finding about the gene and the disease.
urinary tract infection (30 papers, 2009 to 2025). "In a prospective cohort study involving elderly individuals living in the community, those with higher urinary uromodulin concentrations in the top quartile had a reduced risk of urinary tract infection events compared to those in the lowest quartile." (PMID 37835820, 2023). "Remarkably, this protective effect of uromodulin remained significant even after accounting for classical urinary tract infection risk factors." (PMID 37835820, 2023). "The decreased susceptibility to bladder and urinary tract infections appears to be a result of physical interactions between polymeric uromodulin in the urine and bacteria." (PMID 35163625, 2022). "Studies have shown that UMOD knockout mice had lower creatinine clearance and were more susceptible to urinary tract infections." (PMID 35741705, 2022). "UMOD encodes uromodulin, which is released in the urine and plays a protective role against urinary tract infections and ischemia-induced acute kidney injury, as shown in studies of Umod-deficient animals." (PMID 24391588, 2013). "Uromodulin can bind to type-1 fimbriated E coli, the most common pathogen causing urinary tract infections." (PMID 19529781, 2009). "A comprehensive investigation involving a cohort of 953 community-dwelling elderly subjects enrolled in the Cardiovascular Health Study revealed that individuals exhibiting elevated urinary uromodulin levels at baseline experienced a reduced risk of urinary tract infections." (PMID 37835820, 2023). "In addition to its functions in the TAL, uromodulin is associated with cast formation in multiple myeloma, protection against urinary stones, and protection against urinary tract infections." (PMID 36012675, 2022). "Excretion of uromodulin in urine may provide defense against urinary tract infections caused by uropathogenic bacteria." (PMID 22415778, 2012). "The frequency of the major allele of the UMOD promoter variant rs4293393, which is linked to increased uromodulin expression levels, exhibits a consistent correlation with pathogen diversity and the prevalence of antibiotic-resistant urinary tract infections in the population." (PMID 37835820, 2023). "Numerous animal experiments and clinical investigations corroborate the positive correlation between uromodulin levels and protection against urinary tract infections." (PMID 39049957, 2024). "Uromodulin serves various physiological functions, encompassing the prevention of urinary tract infections, kidney stone formation, involvement in renal ion transport, and immune regulation, among others." (PMID 39049957, 2024). "Autoantibodies against uromodulin are believed to play a role in renal tubular disorders and urinary tract infections and have also been detected in kidney transplant donors and recipients." (PMID 37835820, 2023). "A negative relationship has been observed between urinary levels of uromodulin and urinary tract infection markers." (PMID 37835820, 2023). "Uromodulin functions in TAL/distal ureter electrolyte transport safeguards against urinary tract infection and calcium-containing nephrolithiasis, and aids in topical and systemic immunoregulation." (PMID 36362756, 2022). "Glycoprotein 2 (GP2) and uromodulin (UMOD) filaments protect against gastrointestinal and urinary tract infections by acting as decoys for bacterial fimbrial lectin FimH." (PMID 35273390, 2022). "Important roles for uromodulin include protection against urinary tract infections by binding to type 1-fimbriated uropathogenic E. coli and reduction of kidney stone formation by binding CaOx crystals." (PMID 33968083, 2021). "The protein uromodulin encoded by the UMOD gene is usually highly abundant in urine and is known for its protective mechanisms such as prevention of urinary tract infections." (PMID 30715578, 2020). "Uromodulin is involved in water and electrolyte balance and kidney innate immunity, and it is described as a preventive factor regarding urinary tract infections." (PMID 30715578, 2020).
urinary tract infection (continued). "Uromodulin was also was shown to be protective against urinary tract infections due to its ability to bind urinary tract pathogens like Escherichia coli and preventing their binding to uroplakin receptors." (PMID 31065383, 2019). "Among other functions, uromodulin is involved in the prevention of urinary tract infection, water/electrolyte balance, and kidney innate immunity, and is usually highly abundant in the urine of healthy humans." (PMID 27193112, 2016). "Studies on Umod knockout mice revealed a protective role of UMOD against ascending urinary tract infections e.g. of type 1-fimbriated E. coli, and a protective role against calcium oxalate crystal formation in the kidney." (PMID 25409434, 2014). "Tamm-Horsfall protein (THP), also known as uromodulin, is a glycoprotein exclusively produced by the kidney in the distal loop of Henle and is a defense molecule against urinary tract infection." (PMID 23202302, 2012). "Uromodulin protects against urinary tract infections and is an antioxidant." (PMID 37770878, 2023). "Uromodulin plays a vital role in the urinary innate immune defense, making its biochemical and structural characteristics potential targets for leveraging or adjusting its excretion rates to prevent or treat urinary tract infections." (PMID 37835820, 2023). "Uromodulin has various biological functions, including protection against urinary stone formation and urinary tract infection, and regulation of sodium reabsorption through the activation of the Na+–K+–2Cl− cotransporter (NKCC2) and sodium chloride cotransporter (NCC)." (PMID 36012675, 2022). "UMOD might regulate salt transport and play a protective role in urinary tract infection, the formation of kidney stones, kidney injuries, and innate immunity." (PMID 30744112, 2019). "Another hypothesis suggests that reduced eGFR and hence a reduced number of nephrons will lower the production of uromodulin, a protein exclusively produced by the kidney, which has an increasing focus on its clinical relevance as a protective factor against urinary tract infections." (PMID 38679665, 2024). "Uromodulin (UMOD), the most abundant urinary glycoprotein, protects against urinary tract infections through glycan-mediated pathogen binding; nevertheless, its interactions with commensal bladder microbiota (urobiome) remain unexplored." (PMID 40852033, 2025). "Recent insights point to roles for uromodulin in the regulation of salt transport in the TAL, protection against urinary tract infections (UTIs) and kidney stones and regulation of innate immunity." (PMID 28605509, 2017). "In healthy humans and dogs, uromodulin excretion is normal, and since it has defensive properties against urinary tract infections, there is a negative correlation between its detection and the presence of kidney disease in advanced stages." (PMID 36467666, 2022). "Uromodulin (UMOD, NCBI Gene ID: 7369) is known as Tamm-Horsfall protein, the matrix of the cast, and may act as inhibitor of calcium crystallization and defense against urinary tract infections." (PMID 25275511, 2014).
acute kidney injury (29 papers, 2013 to 2025). Sudden and sustained deterioration of the kidney function characterized by decreased glomerular filtration rate, increased serum creatinine or oliguria. "In line with this, UMOD deficient mice experiencing IRI are at higher risk for acute kidney injury with higher interstitial inflammation and cell infiltration." (PMID 34208140, 2021). "In patients with type 1 diabetes mellitus, low urinary uromodulin levels were associated with an eightfold increased risk of renal failure and cardiovascular disease." (PMID 31065383, 2019). "Reduced urinary uromodulin levels have been linked to an elevated risk of acute kidney injury (AKI) following cardiac surgery." (PMID 37835820, 2023). "Given the association between UMOD and acute kidney injury (AKI), we determined whether AS-UMOD expression is altered in AKI." (PMID 40198127, 2025). "Several association studies have shown the prognostic value of uromodulin (urinary and plasma) in kidney function decline, incident CKD, and acute kidney injury (AKI), which are all well-summarised in recent reviews." (PMID 38236469, 2024). "Experimental studies using uromodulin knockout mice reveal a protective role for this protein in acute kidney injury, down-regulating interstitial inflammation." (PMID 36301848, 2022). "As such, higher uromodulin levels may indicate a higher functional reserve of the kidney with a lower risk of acute kidney injury (AKI): the more uromodulin you have, the higher functional reserve you have in case of post-operative AKI for instance." (PMID 35881244, 2022). "Complete uromodulin deficiency in a knockout mouse model has also been shown to increase susceptibility to kidney injury, suggesting that maintaining or even increasing normal circulating uromodulin levels in acute kidney injury would ameliorate injury." (PMID 35163625, 2022). "HU and gout are mainly associated with ADTKD—uromodulin (UMOD) and ADTKD—renin (REN) genetic forms, sometimes starting in the teenage years but usually preceding development of renal failure." (PMID 32106421, 2020). "One of the specific renal proteins—uromodulin—has been found as urinary biomarker which positively correlates with GFR ratio and decreased uromodulin concentrations have been found in renal failure and diabetic nephropathy." (PMID 28105442, 2016). "Myeloma cast nephropathy (CN), the most frequent cause of dialysis-dependent acute kidney injury (AKI), occurs when filtered FLCs precipitate with uromodulin, causing obstruction of the tubules." (PMID 26466100, 2015). "Erythropoietin, vitamin D and uromodulin are known to mediate kidney–immune crosstalk and their disrupted production could impact morbidity and mortality in sepsis with acute kidney injury." (PMID 35163625, 2022). "A report from the SPRINT trial showed that lower uromodulin in urine was associated with incident acute kidney injury, independent of eGFR and albuminuria." (PMID 34568379, 2021). "In our study, we observed that uromodulin is a prominent protein related to EVs and we may assume that its drop in urine concentrations is related to decreased EV density in patient with renal failure." (PMID 28105442, 2016). "However, in diabetes type I, it was shown that decreased uromodulin excretion was a predictive factor for renal failure and cardiovascular disease in adults." (PMID 23990922, 2013). "Additionally, uromodulin plays a role in acute kidney injury (AKI), where its levels fluctuate in response to tubular damage, offering promise for early diagnosis and risk stratification." (PMID 40519162, 2025). "In vivo studies ischemia–reperfusion injury models of acute kidney injury (AKI) showed increased inflammation and necrosis in kidneys of UMOD gene knockout mice, suggesting a protective role of UMOD in kidney." (PMID 37322316, 2024).
acute kidney injury (continued). "The transgenic line expressing the C147W murine mutant uromodulin showed a clinical phenotype with features of UAKD and renal failure with tubular necrosis at an age of 6 months." (PMID 24205203, 2013). "Lower urinary and serum uromodulin concentration levels are an early indicator of poor tubular function, early stages of CKD and risk of acute kidney injury in non-pregnant adults." (PMID 38236469, 2024).
kidney stone (25 papers, 2006 to 2026). "SNP rs4293393 is located 550 basepairs upstream of UMOD gene on 16p12.3 and has been proved to be associated with nephrolithiasis in a GWAS in Icelandic and Dutch populations." (PMID 28361944, 2017). "In contrast to CKD, the UMOD variant confers protection against kidney stones when studied in 3,617 Icelandic and Dutch kidney stone cases and 43,201 controls (OR = 0.88, P = 5.7×10−5)." (PMID 20686651, 2010). "Furthermore, a low concentration of uromodulin in urine could be a factor predisposing to the recurrence of kidney stones; patients with uromodulin deficiency may require intensified metabolic evaluation and follow-up after lithotripsy procedures." (PMID 40559466, 2025). "The presence of uromodulin in urine has an inhibitory influence on renal calculi formation, lowering the morbidity of urolithiasis in women." (PMID 40559466, 2025). "The higher prevalence of urine uromodulin in women provides an explanation both for the morbidity of urolithiasis and the sex-dependent difference in potassium concentration in renal calculi." (PMID 40559466, 2025). "We detected one monoallelic LP variant in the UMOD gene in a 34-year-old female with CKD stage G3a, bland urinalysis, sporadic kidney stones, and a familial history of CKD." (PMID 40428323, 2025). "After isolation of uromodulin from urine samples, kidney stone patients exhibited significant differences in their biochemical composition compared to the controls." (PMID 37835820, 2023). "The oxidized forms of uromodulin play a significant role in promoting the crystallization and growth of calcium oxalate crystals, which are crucial processes in the formation of kidney stones composed of calcium oxalate." (PMID 37835820, 2023). "Several case-control studies have consistently demonstrated reduced urinary uromodulin levels in individuals with kidney stone formation." (PMID 37835820, 2023). "At present, there are few reports on the specific molecular mechanism of UMOD in kidney stone formation." (PMID 35251369, 2022). "Normal uromodulin in the urine provides several functions, including protection against bacterial infection, maintaining innate immunity, protection against kidney stone formation, and even blood pressure control." (PMID 36140366, 2022). "In contrast, the expression of uromodulin was decreased in the renal tissue of kidney stone patients." (PMID 34395096, 2021). "Uromodulin plays a role in the prevention of kidney stone formation by reducing the aggregation of calcium crystals." (PMID 31065383, 2019). "The presented findings have several clinical implications: medications or treatments increasing the uromodulin levels in urine may provide new possibilities for the prevention of kidney stone formation, especially in men." (PMID 40559466, 2025). "Simultaneously, uromodulin promotes the excretion of potassium—consequently, due to the absorption of calcium ions, this is reflected by a higher concentration of potassium in the renal calculi." (PMID 40559466, 2025). "However, other studies suggested that uromodulin, owing to its presence in kidney stones, is involved in the formation of renal calculi." (PMID 37835820, 2023). "To recapitulate, the prevailing body of genetic and in vivo evidence strongly substantiates the notion that uromodulin primarily acts as a potent inhibitor in the process of kidney stone formation, despite a few studies that may suggest otherwise." (PMID 37835820, 2023). "In our study, interestingly, we verified the molecular mechanism of miR-103a-3p in kidney stones that miR-103a-3p silencing could alleviate oxalate-induced injury in NRK-52E cells by activating the UMOD/TRPV5 axis." (PMID 35251369, 2022).
kidney stone (continued). "Both uromodulin and albumin, the two conditioning film components identified as part of the encrusted areas, are known to bind calcium, raising the possibility that calcium-based crystals commonly present in urine of kidney stone patients are retained on the device surface by the components." (PMID 32962019, 2020). "In addition, an up-regulation of UMOD has been observed in the progression of nephrolithiasis." (PMID 16405725, 2006). "However, our finding of the lack of association between UMOD risk alleles and kidney stone severity suggests that while uromodulin influences kidney stone risk, it may not influence subsequent meaningful clinical outcomes." (PMID 39156495, 2024). "Additionally, it is worth considering that the protective effect of uromodulin against kidney stones might be indirectly mediated by enhancing calcium reabsorption in the DCT through the activity of TRPV5/6 channels, thereby reducing luminal calcium concentration." (PMID 37835820, 2023). "All these findings suggested that UMOD could interact with TRPV5 in the formation of kidney stones, which has not been borne out yet." (PMID 35251369, 2022). "Based on the current understanding of uromodulin's physiological roles derived from murine KO studies and human association studies, one could expect that the lack of functional uromodulin in urine would be reflected in repeated UTIs, kidney stones and/or nephrocalcinosis, polyuria or hypotension." (PMID 28605509, 2017).
hyperuricemia (21 papers, 2016 to 2025). An abnormally high level of uric acid. "UMOD mutations are characterized by a distinctive trait: reduced fractional excretion of uric acid (FeUA), resulting in hyperuricemia that precedes CKD and gout." (PMID 37835820, 2023). "ADTKD-UMOD, a monogenic form of renal fibrosis due to mutations in the UMOD gene encoding uromodulin, is characterized by hyperuricemia, gout, alterations in urinary concentration, and progressive loss of kidney function." (PMID 33671535, 2021). "Genetic testing of eight genes associated with hyperuricaemia (UMOD, HPRT1, PRPS1, MTHFR, REN, HNF1b, URAT1 and G6PC) revealed that the 3 affected members carried a novel heterozygous missense variant (c.674C > G, p.T225R) in the UMOD gene." (PMID 32847529, 2020). "Compared with family members with a single heterozygous UMOD mutation, the three patients with homozygous changes presented with cystic kidneys, earlier onset of hyperuricaemia and a more rapid progression to ESRD." (PMID 28605509, 2017). "Moreover, we identified a potentially pathogenic UMOD mutation in our first case, previously linked to hyperuricemia and uric acid nephropathy, expanding the genetic landscape of KIN." (PMID 40529986, 2025). "Mutations in the UMOD gene may lead to disruption in the tertiary structure of uromodulin, which is responsible for the clinical manifestations of interstitial renal disease, polyuria, and hyperuricemia observed in both MCKD2 and FJHN." (PMID 37835820, 2023). "Mutations in the UMOD gene underlie several kidney diseases, such as MCKD2, FJHN, and glomerulocystic kidney disease with hyperuricemia." (PMID 37835820, 2023). "Many patients have hyperuricaemia and some present early gout flare, based on regulation of transcription of the uromodulin (umod) gene by HNF1B, which is involved in urate transport." (PMID 32864159, 2020). "Decreased urine uromodulin excretion in these diseases leads to nephropathy, interstitial nephritis, hyperuricemia, renal stone formation and renal insufficiency." (PMID 30175088, 2018). "Mutations in UMOD, the gene encoding uromodulin, cause autosomal dominant tubulointerstitial kidney disease uromodulin-related (ADTKD-UMOD), characterised by hyperuricemia, gout and progressive loss of renal function." (PMID 28437467, 2017). "In addition, the defective biogenesis and intracellular uromodulin transport affect the Na–K–2Cl cotransporter resulting in defective urinary concentration and mild volume depletion, secondarily increasing proximal reabsorption of uric acid, leading to hyperuricemia." (PMID 37322316, 2024).